LIMS1 (LIM zinc finger domain containing 1)
Diseases named in the same sentence as LIMS1 in open-access papers (continued):
Sharing a sentence is not in itself a finding about the gene and the disease.
cancer (25 papers, 2006 to 2025). A tumor composed of atypical neoplastic, often pleomorphic cells that invade other tissues. "Notably, LIMS1 has exhibited substantial upregulation in tumor‐associated stromal cells of certain cancers, such as breast carcinomatous tissue, implying that heightened LIMS1 in stroma cells might facilitate cancer progression." (PMID 38618967, 2024). "Its homolog, LIMS1, forms a LIMS1-ILK-Parvin complex with integrin-linked kinase (ILK) and Parvin proteins and participates in the critical regulation of various cancers." (PMID 40755754, 2025). "We observed that many adhesion associated genes, like LIMS1 (PINCH), ILK, or specific integrins, have only been marginally studied as cancer targets in radiation research." (PMID 37206618, 2023). "LIMS1 was significantly upregulated in tumor tissue in Western populations, which is in agreement with its anti-apoptotic role in cancer (log2-fold change: 3.05; adjusted P < 0.05)." (PMID 27857161, 2016). "LIMS1 was found up-regulated in cancer samples and is required for the apoptosis resistance of cancer cells through involving with the ERK-Bim pathway." (PMID 23390598, 2013). "The most prominent adhesion related cancer targets, whose inhibition caused cytotoxicity and radiosensitization, were integrin β1 (ITGB1), Focal adhesion kinase (FAK; PTK2) and Particular Interesting New Cysteine-Histidine rich protein (PINCH1; LIMS1)." (PMID 37206618, 2023). "Among the top 10 DRGs identified for Korean (GSE24375), six genes are GC related (ESRRG, LIMS1, GATA3, GATA6, SOX9, POU2F1) and the other four are cancer related (IRF2, RGS3, MRPL36, FOSB)." (PMID 29745833, 2018). "Like LIMS1, studies have shown that LIMS2 takes part in cancer migration and invasion." (PMID 36276291, 2022). "While a crucial contribution to cancer cell therapy resistance has been reported by us for several FAP, such as β1 integrin, LIMS1, FAK and FHL2, here we identified a number of novel candidates." (PMID 32605308, 2020).
tumor (19 papers, 2006 to 2025). "ILK (Integrin-linked kinase) which interacts with LIMS1 was also overexpressed in PDAC tumours." (PMID 33048956, 2020). "Intriguingly, the knockout of LIMS1 in hepatic cells leads to liver enlargement and tumor development." (PMID 38618967, 2024). "Prior investigations have demonstrated that the association between LIMS1 and RAS suppressor protein 1 (RSU‐1) forms a synergistic complex that effectively inhibits the proliferation and migration of tumor cells." (PMID 38618967, 2024). "Subsequently, proliferation, migration, and invasion assays demonstrated that LIMS1 acts as a pro-tumor gene that promotes the invasion and progression of NSCLC cell lines." (PMID 36901953, 2023). "The transwell assay also revealed that, compared to the control group, the migrated and invaded tumor cells were decreased in H157 cells with decreased LIMS1 expression." (PMID 36901953, 2023). "Furthermore, our findings unveil LIM zinc finger domain 1 (LIMS1) as a pivotal gene mediating RBMS3's tumor‐suppressive effect." (PMID 38618967, 2024). "Further assays verified that LIMS1 may act as a pro-tumor gene and promotes tumor progression, thus presenting as a potential biomarker and therapeutic target in NSCLC." (PMID 36901953, 2023). "Furthermore, RSU1, a suppressor of Ras-dependent oncogenic transformation, was reported to interact with LIMS1, and was attributed to inhibiting cell proliferation and invasion in tumor cells including HCC." (PMID 35805200, 2022). "Altogether, these results revealed that LIMS1 promoted the proliferation, migration, and invasion abilities of NSCLC cell lines, suggesting that LIMS1 may function as a pro-tumor gene and promote tumor progression." (PMID 36901953, 2023).
LIMS1 also shares sentences with these, for which no sentence is quoted: colorectal cancer (6 papers); rectal cancer (3); colorectal tumours (2); dilated cardiomyopathy (2); epidermoid carcinoma (2); head and neck squamous cell carcinoma (2); laryngeal squamous cell carcinoma (2); liver cancer (2); lung carcinoma (2); lymph node metastasis (2); neurodegenerative disease (2); non-small cell lung carcinoma (2); tauopathy (2); aneurysm (1); aortic aneurysm (1); atherosclerosis (1); brain cancer (1); cervix carcinoma (1); chondrodysplasia (1); chronic kidney disease (1); Cognitive impairment (1); glioma (1); heart disease (1); hyperlipidemia (1); infection (1); lung squamous cell carcinoma (1); melanoma (1); mucinous colorectal adenocarcinoma (1); myocardial infarction (1); myopathies (1).
A further 9 diseases each share a sentence with LIMS1 in 1 paper.